PEBP1P2 (phosphatidylethanolamine binding protein 1 pseudogene 2)
Gene: Processed pseudogene on chromosome 2 (85,341,281 to 85,341,838, reverse strand). Ensembl gene ENSG00000270532.
Diseases named in the same sentence as PEBP1P2 in open-access papers:
PEBP1P2 is named in the same sentence as 4 diseases in open-access papers, as found by Europe PMC text mining. Sharing a sentence is not in itself a finding about the gene and the disease. The quoted sentences say what the papers report.
breast carcinoma (1 paper, 2022). "In addition to the transwell assay, we established an orthotopic murine breast cancer model with an experimental tail-vein metastasis model to evaluate the role of PEBP1P2 on metastasis formation in vivo." (PMID 36348434, 2022).
cancer (1 paper, 2022). A tumor composed of atypical neoplastic, often pleomorphic cells that invade other tissues. "Therefore, molecular therapies targeting PEBP1P2 might be an effective treatment strategy against ccRCC and other cancers with low PEBP1P2 levels." (PMID 36348434, 2022).
tumor (1 paper, 2022). "Aside from this, the analysis of the clinical sample and TCGA database indicated that a high PEBP1 expression correlated with a low PEBP1P2 expression in tumor tissues." (PMID 36348434, 2022). "Correspondingly, the clinical sample analysis indicated that KLF13 expression was correlated with PEBP1P2 expression in tumor tissues." (PMID 36348434, 2022). "Besides, PEBP1P2 RNA levels were significantly correlated with advanced T stage, M stage, pathologic stage, and tumor progression." (PMID 36348434, 2022).
PEBP1P2 also shares sentences with these, for which no sentence is quoted: clear cell renal cell carcinoma (1 paper).